EPO (erythropoietin)
Diseases named in the same sentence as EPO in open-access papers (continued):
Sharing a sentence is not in itself a finding about the gene and the disease.
Obesity (continued). "Cerebral EPO contributes to metabolic response, and elevated brain EPO reduces fat mass and hypothalamus inflammation during diet induced obesity in male mice without affecting EPO stimulated erythropoiesis." (PMID 34603036, 2021). "This supports the observation that obesity, inflammation and iron reserves do not affect EPO regulation during pregnancy." (PMID 32244712, 2020). "The protective effect of estrogen to diet induced obesity was demonstrated in ovariectomized mice supplemented with estradiol which was more effective in reducing fat mass than EPO, and fat mass was not further enhanced with estrogen combined with EPO." (PMID 32038269, 2019). "Growing attention has focused on the nonerythropoietic activity of EPO, such as its role in obesity regulation." (PMID 26459940, 2015). "Several factors including obesity-related obstructive sleep apnea, current smoking and COPD may contribute to persistent or intermittent hypoxia that lead to red cell production via EPO stimulation." (PMID 25884723, 2015). "EPO treatment also stimulates STAT3 activation in macrophages and reduces macrophage infiltration in white adipose tissue in a mouse model of diet induced obesity." (PMID 24918289, 2014). "Obesity can also lead to hypoventilation and increased production of RBCs through increased production of erythropoietin, which also was not directly measured in this study." (PMID 23226558, 2012). "Furthermore, the EPO analog ARA290 that activates EPOR in non-erythroid tissue without stimulating erythropoiesis has been shown to positively impact diet-induced obesity and glucose tolerance in mice." (PMID 39996752, 2025). "ΔEPORE mice with EPOR restricted to erythroid tissue exhibit decreased energy expenditure and total activity, an age-dependent increase in obesity, and a decrease in glucose tolerance and insulin sensitivity, suggesting that EPO signaling in non-erythroid tissue promotes a lean phenotype." (PMID 39996752, 2025). "In this study we aimed to describe the relationship between EPO and iron nutrition status during nonanemic pregnancy, and to explore whether obesity and inflammation influence erythropoiesis and red cell indices." (PMID 32244712, 2020). "This review highlights examples of EPO protective activity in select non-hematopoietic tissue with emphasis on metabolic response mediated by EPOR expression in fat and brain and sex-specific regulation of fat mass and inflammation associated with diet induced obesity." (PMID 34603036, 2021). "However, no clinical studies have yet examined EPO’s anti-obesity effect in humans." (PMID 28288167, 2017). "This review summarizes the anti-inflammatory roles of EPO in obesity-related metabolic dysfunction, particularly in white adipose tissue (WAT) and the liver, and discusses the therapeutic potential of non-hematopoietic EPO analogs." (PMID 40697664, 2025). "EPO administration increases BMSC progenitors and bone marrow endothelial cells and restores hematopoietic and non-hematopoietic subsets of cells that are altered during obesity." (PMID 32121294, 2020). "EPO mimetic peptides were designed to stimulate non-erythroid EPO-like activity without increasing hematocrit such as ARA290 that has been suggested to benefit human metabolic control and neuropathy, raising the potential for EPO mimetics to treat obesity and metabolic syndromes." (PMID 39284834, 2024).
breast carcinoma (50 papers, 2002 to 2025). "Recently, miR-125b was validated to target erythropoietin and its receptor and their expression is associated with metastatic potential in breast cancer." (PMID 25605244, 2015). "Erythropoiesis-stimulating agents, such as recombinant human erythropoietin, have been associated with higher mortality rates in patients with head and neck cancer, breast cancer, and non-small cell lung cancer." (PMID 24681760, 2014). "However, treating breast cancer patients with EPO has been associated with poor prognosis and decreased survival." (PMID 36078139, 2022). "Hypoxia-inducible factor-1α (HIF-1α) has become a significant therapeutic target for breast cancer and other cancers by regulating the expression of downstream genes such as erythropoietin, thereby improving cell survival in hypoxic conditions." (PMID 40421268, 2025). "Erythropoietin supports the survival of endothelial cells, neurons subjected to hypoxia; thus, it significantly supports the survival of tumor cells in breast cancer, head and neck tumors, and colorectal cancer." (PMID 37894821, 2023). "Our data and meta-analysis of published datasets strongly argue with the latter report and are in line with most of the other studies on this topic, including involvement of EPO in NB and breast cancer cell survival." (PMID 34556815, 2021). "MiR-125b has been found to constrain breast cancer cell proliferation, invasion and migration by targeting erythropoietin (EPO) and EPO receptors and ERBB2 25-27." (PMID 32328182, 2020). "Our results indicate that recombinant erythropoietin increased the number of tumor-initiating cells in established breast cancer lines in vitro." (PMID 30700319, 2019). "Since EpoR are highly expressed in breast cancers, EPO coating on EPO-TAMNLC surfaces serve as the ligand in the binding of the nanoparticles to EpoR on the breast cancer cells." (PMID 31291309, 2019). "In breast cancer therapy, EPO-TAMNLC is expected to effectively inhibit tumour development and progression at doses lower than that required with oral TAM therapy." (PMID 31291309, 2019). "We characterized the LA7 cells to ascertain the suitability of LA7 cell-induced rat mammary gland tumor as a model for determination of the anti-breast cancer properties of EPO-TAMNLC." (PMID 31291309, 2019). "Based on the results, it is postulated that EPO-TAMNLC exerts active targeting effect on breast cancers through the EpoRs on breast cancer cells." (PMID 31291309, 2019). "As expected, we found an inverse correlation between hemoglobin and serum erythropoietin levels in a cohort of breast cancer patients scheduled to undergo radiation treatment and mean serum erythropoietin levels correlated with disease stage." (PMID 30700319, 2019). "The data presented in the present study indicate that more advanced breast cancers more efficiently suppress erythropoiesis even in the presence of elevated serum erythropoietin levels." (PMID 30700319, 2019). "The underlying mechanisms are incompletely understood, but low hemoglobin levels trigger the secretion of erythropoietin, which has been shown to increase the number of radiation and chemotherapy-resistant tumor-initiating cells in breast cancer and glioma." (PMID 30700319, 2019). "Here we have investigated the effects of EPOR knockdown in two human breast cancer cell lines and in a xenotransplantation model designed to mimic EPO therapy in breast cancer patients." (PMID 28418910, 2017). "In a xenotransplantation model, designed to simulate recombinant EPO therapy in breast cancer patients, knockdown of EPOR markedly reduced tumor growth." (PMID 28418910, 2017). "In vitro studies in breast cancer cell lines have demonstrated that autocrine/paracrine production of EPO and EPOR under hypoxia contributes to cell survival and proliferation." (PMID 28430808, 2017). "Here, we have examined the functional role of the EPO-EPOR axis in pre-clinical models of breast cancer." (PMID 28418910, 2017).
breast carcinoma (continued). "EPO expression in turn stimulates tyrosine phosphorylation, DNA synthesis, migration of vascular endothelial cells, angiogenesis and proliferation in breast cancer cells." (PMID 29108271, 2017). "EPO increases MYC expression in erythroid progenitor cells and we found that EPO increases MYC expression in both breast cancer cell lines." (PMID 28418910, 2017). "Here we have examined the impact of EPOR modulation in breast cancer cell lines and in a xenotransplantation model designed to simulate EPO treatment in cancer patients." (PMID 28418910, 2017). "Hypoxia is associated with the induction of EPO and EPOR mRNA expression along with their related proteins in breast carcinomas." (PMID 29108271, 2017). "EPO has been reported to increase lymph node lymphangiogenesis and lymph node tumor metastasis in a mouse model of breast cancer." (PMID 28418910, 2017). "Scenarios comprise CHOP chemotherapy for the treatment of aggressive non-Hodgkin’s lymphoma disease with different dosing and timing schedules of Filgrastim or Pegfilgrastim and breast cancer therapies supported by Filgrastim and EPO." (PMID 24886056, 2014). "Recent research revealed that EPO/EPOR contributes to the mechanism of trastuzumab resistance in breast cancer cell line SKBR3, and EPOR downregulation can reverse the resistance to trastuzumab." (PMID 25426117, 2014). "The Breast Cancer Erythropoietin Survival Trial (BEST) was one of the first chemotherapy studies to report an association between increased mortality and ESA use." (PMID 22395661, 2012). "A large clinical trial, the breast cancer erythropoietin survival trial (BEST) was terminated early because of an increased number of patients experiencing early demise in the EPO arm." (PMID 18382691, 2008). "Fluorescently-labeled R3230-GFP mammary carcinoma cells were co-injected with erythropoietin into window chambers." (PMID 17579721, 2007). "We evaluated the activation of EPO-dependent signal transduction in R3230 mammary carcinoma cells engineered to express the constitutively active EPOR-R129C mutant." (PMID 17579721, 2007). "Exogenous recombinant erythropoietin (rEpo) has been recently shown to increase tumour oxygenation in a mammary carcinoma model." (PMID 16288305, 2005). "EPO-TAMNLC is safe for use in the treatment of breast cancers." (PMID 31291309, 2019). "Furthermore, previous preclinical reports indicated expansion of the pool of breast cancer-initiating cells when erythropoietin was combined with ionizing radiation." (PMID 30700319, 2019). "Together these findings led us to hypothesize that elevated endogenous erythropoietin levels could similarly increase the aggressiveness of breast cancer and potentially impair treatment outcomes." (PMID 30700319, 2019). "In a prospective study, we evaluate whether elevated endogenous serum erythropoietin levels correlate with increased numbers of tumor-initiating cells in a cohort of breast cancer patients who were scheduled to undergo radiation treatment." (PMID 30700319, 2019). "In the present study, we demonstrate that in a cohort of breast cancer patients, while endogenous erythropoietin levels were negatively correlated with hemoglobin levels, higher erythropoietin levels correlated with lower numbers of putative breast cancer-initiating cells (BCICs) in the tumors." (PMID 30700319, 2019). "Finally, we sought to study if elevated endogenous erythropoietin would increase the number of tumor-initiating cells in breast cancer patients." (PMID 30700319, 2019). "A coherent picture has emerged, firmly linking the EPO-EPOR axis to breast cancer progression." (PMID 28418910, 2017). "we initiated a randomised neoadjuvant clinical trial comparing two different schedules of neo-adjuvant epirubicin (EPI) single treatment, a “1-21 schedule” versus “weekly schedule” plus or minus the concomitant administration of EPO in patients with locally advanced breast cancer." (PMID 29108271, 2017).
breast carcinoma (continued). "In addition, KIAA0101 and EPO expression were found to be positively correlated in the dataset of 23 renal carcinoma, 164 bladder carcinoma and 159 breast carcinoma samples." (PMID 26575329, 2016). "Moreover, EPO/EPOR promoted tumorigenesis in genetically engineered mouse models of breast cancer by activating JAK/STAT signaling in breast tumor-initiating cells (TICs) and promoted its self-renewal." (PMID 25426117, 2014). "Moreover, we describe one of the mechanisms that regulate EPO-EPOR expression in breast cancer that is miRNA-dependent." (PMID 24165569, 2013). "In 2001, Acs and coworkers first described an increased expression of EPO-EPOR in breast cancer samples and cell lines, hypothesizing a paracrine loop able to sustain cell proliferation." (PMID 24165569, 2013). "Similarly, the Breast Cancer Erythropoietin Trial (BEST) examining the use of rhEPO in women with metastatic breast cancer receiving first-line chemotherapy was terminated prematurely owing to an observed higher mortality in the rhEPO group." (PMID 17299396, 2007). "Conversely, targeting endogenous EPO using recombinant soluble EPOR (sEPOR) or a neutralizing anti-EPO monoclonal antibody co-injected into window chambers with mammary carcinoma cells inhibits the initiation of tumor angiogenesis and delays growth during the initial stages of tumorigenesis." (PMID 17579721, 2007). "In addition, it has been reported that EPO induces phosphorylation of mitogen-activated protein kinase family members such as Erk-1/2 in human ovarian cancer cells and phosphorylation of Akt in neuroblastoma cells and breast cancer." (PMID 28415825, 2017). "In this study, we describe erythropoietin (EPO) and erythropoietin receptor (EPOR) as novel targets of miR-125b and we tested the hypothesis of an association between miRNA/targets expression and clinical outcomes in breast cancer." (PMID 24165569, 2013). "The EPO-TAMNLC is a physiochemically stable and efficacious drug delivery system for the treatment of breast cancers." (PMID 31291309, 2019). "In conclusion, EPO-TAMNLC is not only a unique drug delivery system because of the dual drug-loading feature, but also potentially highly specific in the targeting of breast cancer tissues positive for ERs and EpoRs." (PMID 31291309, 2019). "Our previous study showed that combination EPO and tamoxifen (TAM) treatments produced greater rat mammary tumor regression than TAM alone." (PMID 31291309, 2019). "Other authors have shown that the EPO/EPOR axis plays an important role in the regulation of the migration and invasion of breast cancer cells." (PMID 28430808, 2017). "For the prognostic value of KIAA0101 and EPO expression in the primary tumors, GSE33371 (renal carcinoma), GSE13507 (bladder carcinoma) and GSE1456 (breast carcinoma) were downloaded from Gene Expression Omnibus (GEO) database." (PMID 26575329, 2016). "MiR-125b, which targets erythropoietin (EPO) and its receptor (EPOR) as well as ERBB2, is found to be one of the most downregulated miRNAs in breast cancer." (PMID 25849621, 2015). "Among them, we validated erythropoietin (EPO) and its receptor (EPOR) - frequently overexpressed in breast cancer - as true targets of miR-125b." (PMID 24165569, 2013). "We validated the opposite modulation of miR-125b, EPO and EPOR by RT-qPCR in a cohort of 42 breast cancer patients and 13 normal samples collected at the University of Ferrara." (PMID 24165569, 2013). "In this work, we confirmed the down-regulation of miR-125b and the up-regulation of EPO and EPOR in a large panel of breast cancers." (PMID 24165569, 2013). "Taken together our results show a mechanism for EPO/EPOR and ERBB2 co-regulation in breast cancer and confirm the importance of miR-125b in controlling clinically-relevant cancer features." (PMID 24165569, 2013).
breast carcinoma (continued). "In breast cancer, a phase III study on the use of EPO was stopped because of increased mortality, tumour progression and increased incidence of thrombotic and vascular events." (PMID 23305401, 2013). "In this study, we investigated the effect of human recombinant erythropoietin (rHuEPO) on cell proliferation, early gene response and the expression of EPOR isoforms in the MCF-7 breast cancer cell line." (PMID 24294184, 2013). "Erythropoietin (EPO) and its receptor (EPOR) were validated as targets of miR-125b by luciferase assay and their expression was assessed by RT-qPCR in 42 breast cancers and 13 normal samples." (PMID 24165569, 2013). "Cell numbers were tested for correlation with serum levels of angiopoietin-2, erythropoietin, endostatin, endoglin, VEGF and sVCAM-1 as well as clinical and pathological features of breast cancer disease." (PMID 16450002, 2006). "Several reports have suggested that EPO and EPO stimulating agents could promote tumor cell proliferation through its specific receptor (EPOR) and hypoxia in head and neck tumors, breast cancer and HCC." (PMID 36961524, 2023). "Recombinant erythropoietin, simultaneously with the action of ionizing radiation, led to the phenotypic conversion of non-stem cells into tumor-inducing breast cancer cells together with the re-expression of pluripotency factors c-Myc, Sox2, and Oct4." (PMID 37894821, 2023). "Such non-responsiveness to EPO has been previously observed in EPOR-expressing A549 cells as well as in some breast cancer cell lines." (PMID 36052260, 2022). "EPO induced the activation of PI3K/AKT and MAPK pathways in human breast cancer cell lines." (PMID 28418910, 2017). "Moreover, exposure of HER2 and EPOR dual-positive breast cancer cell lines to trastuzumab inhibited AKT and ERK phosphorylation, but the inhibition was reduced by simultaneous treatment with recombinant EPO." (PMID 28418910, 2017). "Given that EPO-induced signalling components are more readily detected in the Rama 37 cells overexpressing EPOR, the results of the two studies are in good agreement and corroborate the idea that the EPO-EPOR axis is important in breast cancer progression." (PMID 28418910, 2017). "On the other hand, co-injection of a neutralizing anti-EPO antibody and rhEPO or targeting endogenous EPO using sEPOR inhibits the initiation of tumor angiogenesis of rat R3230-GFP mammary tumor cells and leads to growth delays during the initial stages of tumorigenesis." (PMID 28703764, 2017). "The mechanism of EPO-EPOR and HER2 co-regulation in breast cancer was confirmed by miR-125b, which is downregulated in metastatic breast cancers and a significant positive correlation between EPOR and HER2 levels that are both targets of miR-125b was demonstrated." (PMID 25426117, 2014). "Although not in RCC, it is worth mentioning the adverse effects of EPO administration in other cancers, especially breast cancer and head and neck cancer." (PMID 23305401, 2013). "In conclusion, we demonstrated that the tumor-suppressive miR-125b is able to modulate erythropoietin/ erythropoietin receptor axis in breast cancer and display a negative correlation with its metastatic potential." (PMID 24165569, 2013). "Indeed, both EPO and EPOR 3′UTRs have at least one target sequence for miR-125b that responded to a miR-125b mimic transfection in the context of breast cancer cells." (PMID 24165569, 2013). "Much evidence has shown that high expression of EPO is associated with poor prognosis in HCC and breast cancer, but its role in nonresponse to TACE is still unknown." (PMID 36213835, 2022). "In this study, the tamoxifen-loaded erythropoietin-coated nanostructured lipid carriers (EPO-TAMNLC) were developed to enhance the anti-cancer properties and targetability of TAM, using EPO as the homing ligand for EPO receptors (EpoRs) on breast cancer tissue cells." (PMID 31291309, 2019). "EPO does not compromise the efficaciousness of breast cancer chemotherapeutics." (PMID 31291309, 2019).